DOLK (dolichol kinase)
Description:
Catalyzes CTP-mediated phosphorylation of dolichol, the terminal step in de novo dolichyl monophosphate (Dol-P) biosynthesis. Dol-P is a lipid carrier essential for the synthesis of N-linked and O-linked oligosaccharides and for GPI anchors.
Synonyms: KIAA1094; TMEM15; DK1; CDG1M; DK; SEC59
Tractability: Antibody: UniProt predicts a signal peptide or a membrane-spanning region.
Gene: Protein-coding gene on chromosome 9 (128,945,530 to 128,947,603, reverse strand). Ensembl gene ENSG00000175283.
Subcellular location: Endoplasmic reticulum membrane
Subcellular location (Human Protein Atlas): Nucleoli; Nucleoplasm; Cytosol
Pathways (Reactome):
Disease: Defective DOLK causes DOLK-CDG
Metabolism of proteins: Synthesis of dolichyl-phosphate
Gene Ontology:
Molecular function: dolichol kinase activity; protein binding
Biological process: dolichyl monophosphate biosynthetic process
Cellular component: endoplasmic reticulum membrane; nucleolus
Genetic constraint (gnomAD): Loss-of-function variants: 20 observed, 33.86 expected, observed/expected ratio (o/e) 0.59, 90% interval 0.41 to 0.86. The upper end of that interval is the gene's LOEUF score, 0.86, which puts it in group 3 of 6, group 1 being the genes least tolerant of losing a copy. Missense variants: 594 observed, 718.39 expected, observed/expected ratio (o/e) 0.83, 90% interval 0.77 to 0.88. Synonymous variants: 309 observed, 305.28 expected, observed/expected ratio (o/e) 1.01, 90% interval 0.92 to 1.11.
Gene-disease validity (ClinGen):
ClinGen rates the evidence that DOLK causes each of these diseases.
DK1-congenital disorder of glycosylation (autosomal recessive): Definitive. DK1-CDG is characterized by muscular hypotonia and ichthyosis.
Homologues: Orthologues: chimpanzee DOLK (100% identical), macaque DOLK (99% identical), pig DOLK (96% identical), rat Dolk (95% identical), mouse Dolk (95% identical), dog DOLK (94% identical), guinea pig DOLK (93% identical), rabbit DOLK (91% identical), tropical clawed frog dolk (68% identical), zebrafish dolk (63% identical), Drosophila melanogaster Dolk (28% identical), Caenorhabditis elegans dolk-1 (17% identical).
Diseases named in the same sentence as DOLK in open-access papers:
DOLK is named in the same sentence as 27 diseases in open-access papers, as found by Europe PMC text mining. Sharing a sentence is not in itself a finding about the gene and the disease. The quoted sentences say what the papers report.
dilated cardiomyopathy (4 papers, 2011 to 2023). Cardiomyopathy which is characterized by dilation and contractile dysfunction of the left and right ventricles. "A rare case of dilated cardiomyopathy (DCM) was reported in one of the two families with DOLK deficiency (DOLK-CDG, MIM 610768)." (PMID 37250845, 2023). "In a cohort of 11 patients, presenting primarily with nonsyndromic dilated cardiomyopathy at the age of 5–13 years, we identified three separate mutations in DOLK as the underlying cause of disease." (PMID 22242004, 2011). "In conclusion, we have shown that dolichol kinase deficiency results in abnormal N-glycosylation and reduced O-mannosylation of alpha-dystroglycan, leading to a clinical phenotype of dilated cardiomyopathy." (PMID 22242004, 2011).
epilepsy (4 papers, 2011 to 2021). A brain disorder characterized by episodes of abnormally increased neuronal discharge resulting in transient episodes of sensory or motor neurological dysfunction, or psychic dysfunction. "A few cases with biallelic pathogenic variants in DOLK (OMIM *610746) with severe multi-organ involvement encompassing profound muscular hypotonia, ichthyosiform skin, nystagmus, epilepsy, and pulmonary infections leading to death within the first months of life have also been described." (PMID 34956305, 2021).
ichthyosis (3 papers, 2011 to 2022). Disorders of cornification that are characterized by visible scaling and/or hyperkeratosis of most or all of the skin. "CDG linked to ichthyosis or ichthyosiform dry skin with variable neurologic and multi-organ involvement are due to deficiencies within the dolichol (DOLK-, SRD5A3-CDG) and the GPI (glycosylphosphatidylinositol) anchor biosynthesis pathway (PIGL-CDG, MPDU1-CDG)." (PMID 34956305, 2021).
congenital disorder of glycosylation type Im (2 papers, 2024 to 2025). "According to the Online Mendelian Inheritance in Man (OMIM) database, diseases associated with DOLK, DPM1, and DPM2 variants are designated as congenital disorders of glycosylation, type Im (CDG1M; 610768), type Ie (CDG1E; 608799), and type Iu (CDG1U) (615042), respectively." (PMID 39998573, 2025).
dystroglycanopathy (2 papers, 2022 to 2023). "DOLK is known to be pathogenic for a form of α-dystroglycanopathies." (PMID 35409321, 2022). "DOLK variants have also been reported in patients showing a phenotype which overlaps CDG and dystroglycanopathy (DGpathy), with defective N-glycosylation and reduced O-mannosylation." (PMID 37250845, 2023).
Hypoglycemia (2 papers, 2020 to 2021). A decreased concentration of glucose in the blood. "Other CDG in which hypoglycemia has been reported are DOLK‐CDG, ALG6‐CDG, ALG3‐CDG, and ALG12‐CDG." (PMID 32071842, 2020).
gastroesophageal reflux (1 paper, 2022). "Dysphagia and/or gastroesophageal reflux was present in ALG1‐, ALG6‐, ALG11‐, ALG12‐, DPM1‐, and DOLK‐CDG." (PMID 35279850, 2022).
microcytic anemia (1 paper, 2013). Anemia in which the red blood cell volume is decreased. "We expand the clinical phenotype with the observation of microcytic anemia and report on the laboratory abnormalities of abnormal coagulation and normal endocrine studies in dolichol kinase defect." (PMID 22327749, 2013).
muscular dystrophy (1 paper, 2019). Muscular dystrophy (MD) refers to a group of more than 30 genetic diseases characterized by progressive weakness and degeneration of the skeletal muscles that control movement. "DOLK‐CDG, DPM1‐CDG, DPM2‐CDG, and DPM3‐CDG are defects in the DPM synthesis showing both CDG‐I abnormalities and reduced O‐mannosylation of alpha‐dystroglycan (αDG), which leads to muscular dystrophy‐dystroglycanopathy." (PMID 31741824, 2019).
cancer (4 papers, 2018 to 2022). A tumor composed of atypical neoplastic, often pleomorphic cells that invade other tissues. "Since irreparable structural mutations in cells may result in cancer occurrence, we then determined the genetic alterations of SRD5A3, DOLK, SRD5A1, and HSD17B3 in BC." (PMID 34465365, 2021). "Only three genes including Dolichol Kinase (DOLK), TruB Pseudouridine Synthase Family Member 2 (TRUB2), and Ubiquitin Related Modifier 1 (URM1) were identical between normal and cancer tissues." (PMID 30388870, 2018).
neurological disorders (3 papers, 2019 to 2025). "Moreover, DOLK variants are listed among ASD risk genes in patients with neurological disorders and ASD." (PMID 39859496, 2025).
genetic disorders (1 paper, 2023). "Various studies have shown that DOLK is one of the candidate genes causing CDG, and mutations in this gene have also been associated with other genetic disorders such as DCM." (PMID 37250845, 2023).
tumor (1 paper, 2022). "On the other hand, a series of other genes acting earlier in this pathway are overexpressed in tumor cells, namely DOLK, DPM1/2/3, POMGNT1, B3GALNT2, POMK and FKTN, hence exerting instead a pro-oncogenic role." (PMID 36494657, 2022).
DOLK also shares sentences with these, for which no sentence is quoted: microcephaly (2 papers); Aicardi-Goutieres syndrome (1); autosomal recessive dilated cardiomyopathy (1); breast carcinoma (1); cardiac failure (1); cardiomyopathy (1); congenital heart disease (1); congenital muscular dystrophy (1); fructose intolerance (1); Hyperkeratosis (1); Hypsarrhythmia (1); Intellectual disability (1); triple-negative breast carcinoma (1); Walker-Warburg syndrome (1).